PITX1 (paired like homeodomain 1)
Diseases named in the same sentence as PITX1 in open-access papers (continued):
Sharing a sentence is not in itself a finding about the gene and the disease.
osteoarthritis (7 papers, 2012 to 2025). A noninflammatory degenerative joint disease occurring chiefly in older persons, characterized by degeneration of the articular cartilage, hypertrophy of bone at the margins and changes in the synovial membrane. "PITX1 plays a critical role in hind limb formation during fetal development, while loss of expression is associated with primary knee/hip osteoarthritis in aging humans." (PMID 30837642, 2019). "Polymorphisms in PITX1 have also been recently associated with osteoarthritis in a Chinese population." (PMID 22808055, 2012). "To further understand how PITX1 regulation could be associated with the progression of osteoarthritis, we investigated potential positive regulators." (PMID 27802335, 2016). "Pitx1 is thus an osteoarthritis gene with a key role in disease onset and progression that likely involves its effects on joint morphology and the developmental programs that are re-initiated during disease progression." (PMID 33473114, 2021). "We identify 14 genes with functional involvement in osteoarthritis pathogenesis, including the homeobox gene Pitx1, and functionally characterize 6 candidate human osteoarthritis genes in mouse models." (PMID 33473114, 2021). "Interestingly, aging Pitx1+/− heterozygous mice that are normal at birth progressively develop osteoarthritis-like lesions in their hip/knee cartilage along with a drastic increase in cortical and trabecular bone formation." (PMID 30837642, 2019). "Results from the present study reveal, for the first time, that PITX1 is a direct target of E2F1, and other targets may also be regulated in a similar manner during the progression of osteoarthritis." (PMID 27802335, 2016).
autism (5 papers, 2007 to 2024). Persistent deficits in social interaction and communication and interaction as well as a markedly restricted repertoire of activity and interest as well as repetitive patterns of behavior. "Previous studies have shown that variants in SLC25A12, EN2, ATP2B2 and PITX1, have an association with autism." (PMID 20678243, 2010). "In this study, we have found a significant association between autism and polymorphisms of PITX1, a paired-like homeodomain transcription factor involved in hormonal regulation." (PMID 18053270, 2007). "Strong and consistent association was observed between a 2 SNPs within PITX1 and autism." (PMID 18053270, 2007). "Our data suggest that PITX1, a key regulator of hormones within the pituitary-hypothalamic axis, may be implicated in the etiology of autism." (PMID 18053270, 2007). "Using single point association analyses and haplotype analyses, we found significant evidence for an association of autism with PITX1 but not with H2AFY or NEUROG1." (PMID 18053270, 2007). "Its putative involvement in autism is supported by evidence documenting abnormal levels of hormones such as ACTH, beta-endorphin, and cortisol in autistic individuals and by the fact that these hormones are downstream of PITX1." (PMID 18053270, 2007).
glioblastoma (5 papers, 2021 to 2024). The most malignant astrocytic tumor (WHO grade IV). "Thus, circular RNA PITX1 acts as a ceRNA to regulate the miR-379–5p/MAP3K2 axis and promotes glioblastoma growth." (PMID 35883576, 2022).
glioma (4 papers, 2020 to 2025). A benign or malignant brain and spinal cord tumor that arises from glial cells (astrocytes, oligodendrocytes, ependymal cells). "It was shown that circ-PITX1 knockdown inhibited glycolysis and made glioma cells sensitive to radiation treatment." (PMID 36358938, 2022). "The expression of miR-329-3p was decreased in glioma samples compared to the control, and miR-329-3p expression was negatively correlated with circ-PITX1 in glioma samples, suggesting that the oncogenic effect of circ-PITX1 was achieved by sponging miR-329-3p." (PMID 36358938, 2022). "By introducing both the overexpression vector circ-PITX1 and the glycolysis inhibitor 2-DG into glioma cells, it was demonstrated that circ-PITX1 overexpression promoted the glycolytic process and radiation resistance, but 2-DG counteracted this promotion." (PMID 36358938, 2022). "CircPITX1, produced via splicing of PITX1, could aggravate glioma progression by miR-1304/ERBB4 axis, acting as an indicator of poor prognosis of patients with glioma." (PMID 32190004, 2020). "These and other SMAD3/PITX1 downstream targets also present different expression levels in high-grade glioma (HGG) and low-grade glioma (LGG) tissue samples from the human protein atlas." (PMID 37833281, 2023). "GB cells exhibit extensive chromatin rewiring, reshaping the enhancer landscape and regulatory chromatin loops to sustain transcriptional programs that promote neuron–glioma interactions, with key transcription factors (TFs) like SMAD3 and PITX1 orchestrating these adaptations." (PMID 40685688, 2025). "Further, the lack of circ-PITX1 inhibited glioma cell viability, glycolysis, the ability to form radiation-resistant clones in vitro, and tumor growth in vivo—suggesting that circ-PITX1 is a positive regulator of glioma development." (PMID 36358938, 2022).
head and neck squamous cell carcinoma (4 papers, 2018 to 2023). A squamous cell carcinoma that arises from any of the following anatomic sites: lip and oral cavity, nasal cavity, paranasal sinuses, pharynx, larynx, and salivary glands. "Hypermethylation of exon 3 of PITX1 was significantly associated with the risk of death in patients with head and neck squamous cell carcinomas (HNSCC)." (PMID 32830857, 2020). "Similarly, high PITX1 expression was associated with poor prognosis in lung adenocarcinoma and head and neck squamous cell carcinoma." (PMID 35267575, 2022). "Furthermore, it is noteworthy that in patients with head and neck squamous cell carcinoma, the extent of PITX1 exon 3 methylation within cancerous tissue was markedly elevated in comparison to adjacent normal tissue (PITX1 exon 3 methylation: tumor tissue 58.1%; adjacent tissue 31.7%, P < 0.001)." (PMID 37841446, 2023).
hepatocellular carcinoma (4 papers, 2021 to 2023). A malignant tumor that arises from hepatocytes. "Previous reports showed that LINC00662 could promote M2 macrophage polarization in hepatocellular carcinoma, thus we further explored whether PITX1/LINC00662 could mediate macrophage polarization to affect OS malignancy." (PMID 36334221, 2023). "Overexpressing PTP1B curtails the expression of both p120RasGAP and PITX1 in hepatocellular carcinoma (HCC) cells, resulting in inhibition of the PITX1-p120RasGAP axis." (PMID 37841446, 2023). "Restoration of PITX1 by sorafenib treatment resulted in inhibition of RAS activity in hepatocellular carcinoma (HCC) cell lines." (PMID 34526609, 2021).
liver cancer (4 papers, 2021 to 2025). An epithelial or non-epithelial malignant neoplasm that arises from the liver. "tested the diagnostic ability of PITX1 for liver cancer (n = 63) and compared it with the AFP group." (PMID 37841446, 2023). "Moreover, HNF4α was reported to induce liver cancer cell proliferation and migration, whereas pituitary homeobox 1 (PITX1) exerted tumor suppressor effects in HCC." (PMID 34409028, 2021).
osteoporosis (4 papers, 2019 to 2025). A condition of reduced bone mass, with decreased cortical thickness and a decrease in the number and size of the trabeculae of cancellous bone (but normal chemical composition), resulting in increased fracture incidence. "Furthermore, overexpressed Pitx1 in mice osteoblasts results in severe repression of Sca-1 (Ly6a) that was previously associated with senile osteoporosis." (PMID 30837642, 2019). "Pitx1, which inhibits Wnt pathway and the self-renewal of mesenchymal stem cells, induced senile osteoporosis in mice." (PMID 34660581, 2021). "Several studies suggest a role for the transcription factor PITX1 in bone metabolism and in age-related/dependent osteoporosis (type-II osteoporosis)." (PMID 30837642, 2019). "Our study is the first to demonstrate the novel roles of PITX1 in senile osteoporosis where PITX1 regulates the self-renewal of mesenchymal stem cells or progenitor cells through Sca-1 (Ly6a) repression and, in addition, inhibits the Wnt signaling pathway." (PMID 30837642, 2019). "Given that osteoporosis is a complex and heterogeneous disease, future studies will be required to confirm the contribution of PITX1 in human senile osteoporosis and more specifically, in some subsets of patients suffering from ALL or idiopathic osteoporosis." (PMID 30837642, 2019). "For instance, QKI might be suggested as a biomarker for glucocorticoid-induced osteoporosis, LINC01119 might be identified as a marker associated with osteoporosis risk, and PITX1 might be linked to senile osteoporosis." (PMID 41282593, 2025). "In contrast, Pitx1 overexpression induced osteoporosis by repressing Runx2, ALP, osterix, and OCN while increasing Wnt inhibitors (Sost, Dkk1); lithium chloride partly reversed this, showing how Wnt reactivation may counter senescence-driven bone loss." (PMID 41282593, 2025). "New advances in our understanding of the epigenetics of osteoporosis reveal additional mechanisms by which PITX1 expression could be deregulated in the context of osteoporosis." (PMID 30837642, 2019). "Despite several genome-wide association studies for osteoporosis and/or bone fracture, none of them reported a signal in/or around the PITX1 gene." (PMID 30837642, 2019).
prostate carcinoma (4 papers, 2021 to 2024). A carcinoma that arises from epithelial cells of the prostate gland. "For instance, in prostate cancer and bladder cancer, PITX1 is expressed at low levels and suppresses tumorigenicity by downregulating the RAS pathway through the transcription target RASAL1." (PMID 34868397, 2021). "Oppositely, knockdown of PITX1 in prostate cancer cell lines reduces TERT expression." (PMID 37841446, 2023). "Besides observing experimental evidence of PITX1′s functional role in telomerase regulation, we also found PITX1 serving as a prognostic marker, as concluded from an analysis of more than 15,000 prostate cancer samples." (PMID 35267575, 2022). "We see the clinical application of our results primarily in PITX1 serving as a new biomarker for prostate cancer rather than as a therapeutic target." (PMID 35267575, 2022).
bladder cancer (3 papers, 2020 to 2021). "However, the relationship between PITX1 and RASAL1 in bladder cancer has remained elusive." (PMID 32441304, 2020).
esophageal cancer (3 papers, 2014 to 2020). A primary or metastatic malignant neoplasm involving the esophagus. "PITX1 expression is down regulated in a number of tumor types including lung, colorectal, gastric and esophageal cancer and reduced PITX1 expression has been correlated with decreased overall patient survival." (PMID 26649896, 2015). "PITX1 expression is downregulated in a number of tumour types including lung, colorectal, gastric and esophageal cancer, and reduced PITX1 expression has been correlated with decreased overall patient survival." (PMID 24369427, 2014).
squamous cell carcinoma (3 papers, 2020 to 2023). A carcinoma arising from squamous epithelial cells. "Some studies have also shown that SOX2, PITX1, and Twist1, these molecules are highly expressed in tumor stem cells of squamous cell carcinoma, while their expression levels are low in normal skin tissue." (PMID 37841446, 2023). "Knocking down PITX1’s DNA binding domain (DBD) significantly inhibited the growth of squamous cell carcinoma, with levels of Ki67 and EdU significantly decreasing, as well as decreased SOX2 expression, but KLF4 expression levels increasing." (PMID 37841446, 2023). "PITX1 interacts with SOX2 to promote squamous cell carcinoma maintenance of tumor stem cells, increasing tumor malignancy." (PMID 37841446, 2023). "ChIP-seq and transcriptomic analyses reveal PITX1 as a regulator of squamous carcinogenesis in mice and humans, and PITX1 expression controls bi-stable transcriptional circuits to govern self-renewal and differentiation in squamous cell carcinoma." (PMID 32441304, 2020). "KLF4 expression level are negatively correlated with PITX1 in SCC and suppressing the growth of squamous cell carcinoma in vivo." (PMID 37841446, 2023).
cervical cancer (2 papers, 2020 to 2023). A primary or metastatic malignant neoplasm involving the cervix. "Both PITX1 and SF-1 interact and bind to and promote expression in the hCYP11B1 promoter region in the cervical cancer cell line HeLa." (PMID 37841446, 2023).
head and neck cancer (2 papers, 2017 to 2020). A primary or metastatic malignant neoplasm affecting the head and neck. "PITX1 expression level was found recently to be a novel predictor for treatment response of head and neck cancer." (PMID 28415559, 2017).
hip osteoarthritis (2 papers, 2016 to 2021). "Knockdown of TFDP1 reduced both PITX1 promoter activity and mRNA transcription which caused patients suffering of knee/hip osteoarthritis." (PMID 34285141, 2021). "We previously reported a loss-of-PITX1 expression in patients suffering of knee/hip osteoarthritis (OA)." (PMID 27802335, 2016).
leukemia (2 papers, 2019 to 2023). A malignant (clonal) hematologic disorder, involving hematopoietic stem cells and characterized by the presence of primitive or atypical myeloid or lymphoid cells in the bone marrow and the blood. "For example, cells carrying mutations exclusively in JAK2 specifically upregulated B4GALT1, which is associated with acquisition of drug resistance in leukemia, and cells with mutations in epigenetic modifiers specifically upregulated PITX1, which has been previously implicated in leukemogenesis." (PMID 30765193, 2019). "RUNX1 transcription is regulated by a distal promoter that is directly inhibited by PITX1 through their interaction, thus suppressing T cell development and promoting leukemia." (PMID 37841446, 2023). "PITX1 exhibits heightened expression in 9% of leukemia cases." (PMID 37841446, 2023). "While elevated PITX1 expression does not significantly impact proliferation in the leukemia cell line JURKAT, it does contribute to the upregulation of genes associated with T cell differentiation." (PMID 37841446, 2023).
lung adenocarcinoma (2 papers, 2022). A carcinoma that arises from the lung and is characterized by the presence of malignant glandular epithelial cells. "A recent bioinformatics analysis showed that high PITX1 expression was related to DNA methylation and poor prognosis in lung adenocarcinoma." (PMID 36204311, 2022).
ovarian carcinoma (2 papers, 2021 to 2023). A malignant neoplasm originating from the surface ovarian epithelium. "Regrettably, despite the documented implication of PITX1 in hormone synthesis, the realm of hormone secretion within the ovary and its potential role in conferring resistance to hormone therapy in ovarian cancer remain shrouded in limited information." (PMID 37841446, 2023). "This conspicuous void underscores the imperative of embarking upon comprehensive exploration into the multifaceted role that PITX1 plays in the context of ovarian cancer." (PMID 37841446, 2023). "We experimentally confirmed ER-alpha and PITX1 presence at the DEGs by performing ChIP-seq analysis using the ovarian cancer cell line PEO4." (PMID 34215221, 2021). "Using in silico and in vitro analyses of the DEG promoter sequences, we identified multiple TF binding motifs and validated PITX1 and ERα binding using an ovarian cancer cell line." (PMID 34215221, 2021). "While ERα’s pivotal engagement in the PI3K/AKT and RAS/ERK signaling pathways within the context of ovarian cancer has undergone extensive elucidation, the present study refrained from delving into the specific functions of PITX1 and ERα in this ovarian cancer context." (PMID 37841446, 2023). "However, of the four TFs (PITX1, RARA, FOXF1/A1, and BHLHE41/40) that matched the binding motifs in DEG promoters, only one, FOXA1, has previously been implicated in ovarian cancer specifically." (PMID 34215221, 2021). "Of note, one of the TFs we identified as playing a role in invasiveness, PITX1, has not previously been implicated in ovarian cancer or the MegaTrans complex." (PMID 34215221, 2021). "To confirm the binding of our identified TFs in ovarian cancer, we performed ChIP-seq experiments for FOXA1, PITX1, and ERα in the ovarian cancer cell line PEO4, derived from a poorly differentiated serous adenocarcinoma." (PMID 34215221, 2021). "We found evidence of PITX1 and ERα binding in only one fusion gene, SPINT2, indicating that the majority of the fusion genes identified in this study contribute to ovarian cancer by mechanisms other than this regulatory network." (PMID 34215221, 2021).
pancreatic cancer (2 papers, 2020 to 2025). "Overexpression of BLM, AURKA and PITX1 has previously been linked with poor survival in breast, lung, bladder and pancreatic cancer." (PMID 32899298, 2020).
adenoma (1 paper, 2021). A neoplasm arising from the epithelium. "These authors found that OPLAH alone and/or a combination of a few methylated DNA markers (ARHGEF4, LRRC4, ANTXR1, PITX1) can discriminate adenomas and CRC in LS patients." (PMID 34201893, 2021).
adolescent idiopathic scoliosis (1 paper, 2018). A scoliosis with no known cause arising in adolescent. "The gene of pituitary homeobox 1 (PITX1) has been reported to be down-regulated in adolescent idiopathic scoliosis (AIS), of which the cause has not been well addressed." (PMID 29743058, 2018).
alopecia (1 paper, 2024). Hair loss usually from the scalp. "PITX1 expression in the skin caused extensive, irreversible alopecia that primarily affected the dorsal and ventral skin but occasionally spread to occipital and peripheral regions as well." (PMID 39480496, 2024). "We show that ectopic expression of PITX1 drives alopecia in the murine skin by irreversibly halting the hair cycle and promoting the terminal differentiation of keratinocyte subpopulations that drive hair follicle renewal." (PMID 39480496, 2024).
Arthritis (1 paper, 2021). Inflammation of a joint. "The top-ranked genes associated with arthritis and skeletal disease in humans were Pitx1, coiled-coil domain containing 6 (Ccdc6), HECT and RLD domain containing E3 ubiquitin protein ligase family member 1 (Herc1), nebulette (Nebl), Sh3bp4, and Zfp341." (PMID 33473114, 2021). "Structured literature searching of PubMed and Google Scholar databases identified Bhlhe40, Col4a2 and Pitx1 as the top-ranked candidate genes with publications related to arthritis or skeletal cell biology." (PMID 33473114, 2021).
carcinosarcoma (1 paper, 2020). A malignant tumor composed of a mixture of carcinomatous and sarcomatous elements. "BLM, AURKA and PITX1 were upregulated in each subtype and were more significantly upregulated in carcinosarcoma tumours than endometrioid." (PMID 32899298, 2020).
chondrosarcoma (1 paper, 2025). A malignant cartilaginous matrix-producing mesenchymal neoplasm arising from the bone and soft tissue. "Our findings discovered for the first time that PITX1 correlates with grade in chondrosarcoma, with lower expression at higher grades." (PMID 40342824, 2025).
cleft palate (1 paper, 2016). Cleft palate is a fissure type embryopathy that affects the soft and hard palate to varying degrees. "Among these genes, ablation or mutation of Alx3, Lhx8, Pax3, Pitx1, Shox2, and Zeb2 induces cleft palates in humans and/or mice." (PMID 27329940, 2016).
cutaneous malignant melanoma (1 paper, 2022). "It was reported that the downregulation of PITX1 expression might contribute to the progression of cutaneous malignant melanoma by promoting cell proliferation." (PMID 36204311, 2022).